TFAP4 (transcription factor AP-4)
Diseases named in the same sentence as TFAP4 in open-access papers (continued):
Sharing a sentence is not in itself a finding about the gene and the disease.
lymphoma (2 papers, 2023). A malignant (clonal) proliferation of B- lymphocytes or T- lymphocytes which involves the lymph nodes, bone marrow and/or extranodal sites. "To elucidate the contribution of loss of TFAP4 to c-MYC-driven lymphoma development we compared the expression of genes within certain hallmarks of cancer pathways that TFAP4 has been reported to regulate." (PMID 36894688, 2023). "In Eμ-MYC transgenic B lymphoid cells the loss of TFAP4 dysregulates differentiation resulting in expansion of the rapidly proliferating pre-B cell pool that transforms into fully malignant c-MYC driven lymphoma." (PMID 36894688, 2023). "Interestingly, TFAP4 deficient Eμ-MYC lymphomas all arose at the pre-B cell stage of B cell development." (PMID 36894688, 2023). "We therefore conclude that loss of TFAP4 leads to a block in differentiation during early B cell development, thereby accelerating c-MYC-driven lymphoma development." (PMID 36894688, 2023). "We employed Eμ-MYC/Cas9 doubly transgenic mice and a fetal liver derived HSPC transplantation approach to investigate the tumour suppressive role of TFAP4 during c-MYC-driven lymphoma development." (PMID 36894688, 2023). "We identified TFAP4 as a potent suppressor of c-MYC driven lymphoma development in a previous genome-wide CRISPR knockout screen in primary cells in vivo." (PMID 36894688, 2023). "As TFAP4 is a transcriptional regulator, we next sought to understand how its loss might alter cell signalling pathways to accelerate c-MYC-driven lymphoma development." (PMID 36894688, 2023). "This indicates that increased cell proliferation is not the mechanism by which loss of TFAP4 accelerates c-MYC-driven lymphoma development." (PMID 36894688, 2023). "Additionally, this study revealed that loss of Tfap4, either a single allele or both alleles, accelerated c-MYC-driven lymphoma development in mice." (PMID 36894688, 2023). "In the context of c-MYC-driven lymphoma development, loss of TFAP4 does not alter apoptosis or cell proliferation, as the genes regulating these processes were not differentially expressed in pre-leukaemic pre-B cells lacking TFAP4." (PMID 36894688, 2023). "While TFAP4 was an essential gene in 48% of the cell lines and BCL6 was a lymphoma-specific essential gene, the other 6 in vivo hits showed little evidence of depletion across all cancer types, including 9 osteosarcoma cell lines." (PMID 37938582, 2023). "CRISPR deletion of TFAP4 in Eμ-MYC transgenic haematopoietic stem and progenitor cells (HSPCs) and transplantation of these manipulated HSPCs into lethally irradiated animals significantly accelerated c-MYC-driven lymphoma development." (PMID 36894688, 2023). "Our pre-leukaemic analysis and the immuno-phenotyping of the malignant Eμ-MYC lymphoma cells revealed that the absence of TFAP4 resulted in the accumulation of pre-B cells, indicating a block in B cell development as a possible cause of accelerated c-MYC-driven lymphomagenesis." (PMID 36894688, 2023).
osteosarcoma (2 papers, 2021 to 2023). A usually aggressive malignant bone-forming mesenchymal neoplasm, predominantly affecting adolescents and young adults. "Besides these, we found KLF4, STAT3, BCL6, TFAP2A, and TFAP4 as potential drivers of osteosarcoma metastasis." (PMID 37938582, 2023).
renal fibrosis (2 papers, 2023 to 2025). A final common manifestation of a wide variety of chronic kidney diseases characterized by glomerulosclerosis and tubulointerstitial fibrosis. "In the present study, therefore, TFAP4 may be a regulatory mechanism responsible for NK-1R overexpression in renal fibrosis." (PMID 37033943, 2023). "However, no direct evidence has yet revealed the regulatory role of TFAP4 in renal fibrosis." (PMID 37033943, 2023).
adenoma (1 paper, 2023). A neoplasm arising from the epithelium. "Previous studies revealed that TFAP4 acted as a rate-limiting regulator of adenoma initiation and promoted tumorigenic capability." (PMID 36891298, 2023).
epilepsy (1 paper, 2023). A brain disorder characterized by episodes of abnormally increased neuronal discharge resulting in transient episodes of sensory or motor neurological dysfunction, or psychic dysfunction. "TFAP4 focuses on various cancers, but no research has been conducted on brain injury or epilepsy." (PMID 37483435, 2023).
Liver Diseases (1 paper, 2020). "Lastly, we analyzed the databases for diseases associated with TFAP4 expression and found that “Inflammation”, “ Fatty Liver” and “Liver Diseases” are among the top diseases." (PMID 33235199, 2020).
monocytic leukemia (1 paper, 2011). "We also identified PWMs for transcription factor activating enhancer binding protein 2 (TFAP2A), which is known to activate ADM expression in monocytic leukemia cells, for TFAP4 and for transcriptional activators of the GATA binding protein family." (PMID 22039494, 2011).
Myocardial fibrosis (1 paper, 2025). "Together, these findings demonstrate that Tfap4 deletion mitigates adverse post-MI remodeling by attenuating myocardial fibrosis and preserving cardiac function." (PMID 40612272, 2025).
myocardial infarction (1 paper, 2025). Gross necrosis of the myocardium, as a result of interruption of the blood supply to the area, as in coronary thrombosis. "Our findings suggest that targeting TFAP4 could provide a novel therapeutic approach to mitigate fibrosis and improve cardiac functions in patients with myocardial infarction." (PMID 40612272, 2025).
prostate tumor (1 paper, 2023). "Compared to the normal tissue, the levels of CENPA, ADCK5, FOXM1, TFAP4, and MAPK were up-regulated in prostate tumor tissue, with a decrease in the expression of LGALS3 and BAG3." (PMID 36891298, 2023).
cancer (25 papers, 2013 to 2025). A tumor composed of atypical neoplastic, often pleomorphic cells that invade other tissues. "More importantly, we predicted that TFAP4 overexpression was associated with cancer immunity, and it was, in fact, found to correlate with TMB and MSI." (PMID 33373169, 2021). "Taken together, the findings of the present study provide clues for the association between TFAP4 and cancer immunity." (PMID 33373169, 2021). "Other studies have been carried out to examine the proliferation, overexpression or mutation of TFAP4 in specific types of cancer, but those studies had low sample sizes and diverse methods." (PMID 33373169, 2021). "As a result, it is highly important to carry out a thorough investigation on the association of TFAP4 expression with TMB levels in cancer patients, based on the TCGA‐derived matched data with high quality." (PMID 33373169, 2021). "TFAP4 expression was correlated with tumour mutation burden and microsatellite instability in different cancer types, and enrichment analyses identified TFAP4‐associated terms and pathways." (PMID 33373169, 2021). "TFAP4 is overexpressed in many cancers, including NSCLC111, and its level is an independent predictor of tumor progression and overall survival." (PMID 40155749, 2025). "TFAP4, a member of the bHLH family, has been extensively studied in cancer but remains poorly characterized in fibrosis and tissue remodeling." (PMID 40612272, 2025). "We also revealed that the genes with relatively high expression at 0 h were primarily related to cell growth and proliferation, particularly cancer cell proliferation, such as Tfap4, Rdm1, Ddx39b, Pgam1, and so on." (PMID 36834727, 2023). "Although TFAP4 has been reported in cancer cells to mediate cell fate decisions by diverse mechanisms including the PI3K/Akt pathway, to our knowledge, TFAP4 has not previously been studied in muscle progenitor cells." (PMID 35459735, 2022). "TFAP4 has been disclosed to partake in malignant tumor differentiation, metastasis, and angiogenesis." (PMID 34983307, 2022). "According to CCLE analysis results, TFAP4 displayed inconsistent gene expression levels among various cancer cell lines (P = 1.3e‐11), with biliary tract cells showing a relatively higher gene expression." (PMID 33373169, 2021). "Collectively, our comprehensive pan‐cancer analysis has illustrated the characterization of TFAP4 within cancer cell lines and tissues." (PMID 33373169, 2021). "We also found that most cancer types had a higher number of TFAP4 alternations, and that abnormal TFAP4 expression served as a prognostic factor in some types of cancer, based on both Cox and KM survival analyses." (PMID 33373169, 2021). "In CHOL, OV, UCS and UVM, only one type of immunocyte was correlated with TFAP4 level, while at least two immunocytes were correlated with TFAP4 levels in other cancers." (PMID 33373169, 2021). "Pan‐cancer analysis of TFAP4 is valuable for identifying differential expressions and the role of TFAP4 in many cancer types." (PMID 33373169, 2021). "The present study aimed to demonstrate a comprehensive workflow for pan‐cancer analysis and to extensively investigate the role of TFAP4 as it relates to various cancers." (PMID 33373169, 2021). "This information is of great importance for understanding the roles of TFAP4 in various cancers, so a comprehensive analysis is urgently needed." (PMID 33373169, 2021). "The present study comprehensively analysed TFAP4 expression patterns from 33 types of malignancies, along with the significance of TFAP4 for prognosis prediction and cancer immunity." (PMID 33373169, 2021). "As a result, the present study examined the correlation between TFAP4 levels and the levels of immune infiltration across various types of cancer derived from TIMER." (PMID 33373169, 2021).
cancer (continued). "Transcription factor activating enhancer binding protein 4 (TFAP4) is involved in cancer cell proliferation, epithelial-mesenchymal transition (EMT), stemness, apoptosis, and cellular senescence." (PMID 34141611, 2021). "TFAP4 displayed inconsistent levels of gene expression across the diverse cancer cell lines, and displayed abnormal expression within most malignant tumours, which closely corresponded to overall survival." (PMID 33373169, 2021). "TFAP4 is related to differing degrees of immune infiltration within cancers, which suggests the potential of TFAP4 as an immunotherapy target in cancers." (PMID 33373169, 2021). "It was found that the TFAP4 level was significantly related to the tumour purity for 25 types of cancer types." (PMID 33373169, 2021). "Using CCLE and TCGA, data on various types of cancers with large sample sizes were obtained, which aided in the discovery of abnormal expressions of TFAP4 among different types of cancers." (PMID 33373169, 2021). "For most of the 33 TCGA‐derived cancer types, we detected significantly up‐regulated TFAP4 expression between cancer samples and paired normal samples." (PMID 33373169, 2021). "Based on the results of this study, the TFAP4 level was related to the degree of immune infiltration in a variety of cancers." (PMID 33373169, 2021). "Transcription factor activating enhancer binding protein 4 (TFAP4) is involved in cancer proliferation, metastasis, differentiation, angiogenesis and other biological functions." (PMID 33373169, 2021). "Transcription factor activating enhancer binding protein 4 (TFAP4) is established as a regulator of human cancer genesis and progression." (PMID 31281549, 2019). "Transcription factor activating enhancer-binding protein 4 (TFAP4) is an important regulator in the genesis and progression of human cancers." (PMID 31552102, 2019). "PO-MSCs showed the representative participation of POU2F1 (15.7%, p = 0.03) and TFAP4 (12.5%, p = 0.02) as main transcriptional regulators at upregulated genes, which are related to cancer stem cells, cell cycle, and histone regulation." (PMID 28194153, 2017). "TFAP4 is a basic helix-loop-helix zinc finger transcription factor that acts as a regulatory hub downstream of c-myc113, and promotes the invasion and metastasis of cancer cells by regulating the PI3kinase/AKT pathway and increasing the expression of MMP9114." (PMID 40155749, 2025). "TFAP4 has been shown to play critical roles in modulating transcriptional networks related to cellular differentiation, proliferation, metastasis and other essential biological functions in cancer." (PMID 40612272, 2025). "TFAP4 is a transcription factor known for its role in epithelial-mesenchymal transition and cancer." (PMID 38475725, 2024). "In certain human cancers high levels of TFAP4 expression correlate with poor prognostic outcomes." (PMID 36894688, 2023). "Abnormal miR-373-3p and TFAP4 expressions are critical in many malignant tumors, but it is unclear whether they work in the context of HCC." (PMID 34983307, 2022). "The present study comprehensively analysed the expression of TFAP4 across 33 distinct types of cancers, which revealed that TFAP4 may possibly play a vital role during cancer formation and development." (PMID 33373169, 2021). "Moreover, we have found that TFAP4 can serve as a valuable prognostic biomarker for some types of cancer." (PMID 33373169, 2021). "Studies have shown that transcription factor activating enhancer binding protein 4 (TFAP4) plays a vital role in multiple types of cancer; however, the TFAP4 expression profile is still unknown, as is its value within the human pan‐cancer analysis." (PMID 33373169, 2021).
cancer (continued). "Based on the results of the present study, the TFAP4 level is related to cancer immunity." (PMID 33373169, 2021). "Thereby, TFAP4 is a critical mediator of the onset and development of cancers." (PMID 34141611, 2021). "Based on our results, we found that TFAP4 expression varied among different types of cancer." (PMID 33373169, 2021). "Nonetheless, the role of TFAP4 in these cancers still needs to be further investigated." (PMID 33373169, 2021). "Additionally, data from The Cancer Genome Atlas also indicated high expression levels of TFAP4 in NSCLC tissues." (PMID 31552102, 2019). "TFAP4 has been shown to promote invasion and metastasis in certain types of cancer cell." (PMID 31552102, 2019). "Previous studies have confirmed that overexpression of TFAP4 predicts poor prognosis in various malignancies, alluding to its potential usefulness as a biomarker that can predict the progression and prognosis of cancer." (PMID 31281549, 2019). "Notably, the present study has demonstrated that the TFAP4 level was related to cancer immunity." (PMID 33373169, 2021). "However, further studies are required to determine whether TFAP4 can serve as a predictor for the efficacy of immunotherapy in these types of cancers." (PMID 33373169, 2021). "In addition to the enrichment of guides targeting TM9SF2, LAPTM4A, and genes related to sphingolipid biosynthesis, our analysis detected enrichment for guides targeting several genes associated with cancer and cell proliferation (MLLT3, TFAP4, ZNF217, and DUSP6) (35, –, 38)." (PMID 29921669, 2018). "Interestingly, TFAP4 is under-expressed in CIMP-positive cancers." (PMID 29304767, 2018). "Therefore as a MYC transcriptional target, TFAP4 may play a critical role in cancer cells in concert with deregulated MYC, by coordinating the expression of specific genes that are essential for tumor progression." (PMID 27448979, 2016). "Here, we review the literature on Activating Enhancer-Binding Protein 4 (AP4)/transcription factor AP4 (TFAP4) function and regulation and its role in cancer." (PMID 33567514, 2021). "Thus, in addition to the RSPO3 proteins, HMGA1 and TFAP4 activate the WNT/β-catenin pathway, stimulate cell migration and invasion and promote cancer progression." (PMID 34021172, 2021). "Moreover, TFAP4 levels were significantly correlated with CD4 + T and CD8 + T cell infiltration in 15 types of cancer, B cells in 12 types, neutrophils in 16 types, macrophages in 18 types and dendritic cells in 14 types." (PMID 33373169, 2021). "Taken together with our study, TFAP4 appears to be initially upregulated by MYC or MYCN, after which it cooperatively regulates the same target genes to maximize rapid transcriptional activity in cancer cells." (PMID 27448979, 2016). "Our data support the existence of a regulatory circuit between MYCN and TFAP4, where TFAP4 is directly induced by MYCN, then cooperates with MYCN to regulate a subset of MYCN-target genes involved in cancer cell proliferation and metastasis, nucleotide and protein synthesis and growth." (PMID 27448979, 2016). "Additionally, research on TFAP4 has mainly focused on an individual or limited number of types of cancers, and no available studies have comprehensively examined several types of cancers simultaneously to identify their similarities and differences." (PMID 33373169, 2021).